PROX1 (prospero homeobox 1)
Diseases named in the same sentence as PROX1 in open-access papers (continued):
Sharing a sentence is not in itself a finding about the gene and the disease.
cancer (continued). "In fact, the high expression of PROX1 can promote the formation of lymphatic vessels, which has important pathological significance for lymph node metastasis in cancer." (PMID 35342346, 2022). "It is noteworthy that the prognostic value of PROX1 expression varies among various types of cancer." (PMID 35885529, 2022). "In renal clear cell (RCC) carcinoma, although the expression of PROX1 is lower than that of the surrounding normal tissues, the relatively high expression of PROX1 in cancer tissues is significantly related to poor prognosis." (PMID 35342346, 2022). "Analysis of overall and cancer-specific survival indicated that elevated PROX1 expression in ESCC was significantly correlated with poor prognosis." (PMID 35885529, 2022). "First, PROX1 is reduced in multiple organs and cancer cells in response to metabolic stress or AMPK activation." (PMID 36433955, 2022). "Five hypermethylated regions were in genes previously associated with cancer (TRAP1, SLC38A3, CHRM1, EDN2, and PROX1), while six hypomethylated regions were in genes previously associated with cancer (NUMBL, ALDH1B1, FTCD, FASTKD2, FAM96A, and ARHGAP15)." (PMID 36474183, 2022). "Subsequent functional studies using PROX1 knock-down or over-expression showed that PROX1 is a critical mediator of the anti-cancer effect of rapamycin." (PMID 35159256, 2022). "We also found that expression of the Wnt target gene and cancer stem cell marker Prox1 was decreased in Apc;fl/flSrsf1fl/+." (PMID 35589755, 2022). "We found that PROX1 promoted cancer metastasis by activating WNT signaling in maintaining β-catenin stability and promoting nuclear translocation of β-catenin." (PMID 35342346, 2022). "Liver tumors with high Prox1 expression have a poor prognosis, and cancer cells’ proliferation is significantly accelerated." (PMID 34183992, 2021). "Nevertheless, the exact mechanisms by which Prox1 controls cancer cell proliferation, migration, and invasion are largely unclear." (PMID 34183992, 2021). "HUVECs were incubated on Matrigel-coated plates in conditioned medium collected from cancer cells with PROX1-silenced or control cells treated with siNEG." (PMID 31717665, 2019). "In fact, downstream target molecules of EPHA2, including FAK/Src kinases, are critical regulators of the cancer progression and a pronounced increase of active FAK/Src form expression associates with the PROX1 knock-down." (PMID 31060342, 2019). "PROX1 is significantly engaged in tumorigenesis and plays various tissue-dependent functional roles in cancer dissemination." (PMID 31717665, 2019). "Taken together, observations across different cancer types suggest that PROX1 negatively regulates MMP14 expression." (PMID 29934628, 2018). "Patients with high PROX1 expression had a cancer-specific 5-year survival of 65.6% (95% CI 52.7–78.5), compared to 37.1% (95% CI 30.2–44.0) for those with low expression (p = 0.004, log-rank test)." (PMID 28854215, 2017). "A recent cancer gene profiling study revealed that PROX1 mRNA is significantly decreased in renal cancer tissue compared to adjacent normal tissue." (PMID 24797520, 2014). "Further functional and large scale clinicopathological examinations using various series of cancers are warranted in order to clarify the roles of Prox1 in cancers." (PMID 24647631, 2014). "In contrast, PROX1 was overexpressed in colorectal cancer and found to have a role in promoting cancer progression." (PMID 21559010, 2011). "Recently Prox1 has received great attention because it demonstrates that it plays a more important role in progression of various carcinomas than before." (PMID 23675176, 2010). "Although it has been established that PROX1 is important in the development and metastasis of cancer, it is mostly unknown how it regulates the ability of cancer cells to proliferate, migrate, and invade." (PMID 40660330, 2025). "The LKB1-AMPK axis in cancer cells depends on PROX1 to maintain intracellular BCAAs pools." (PMID 40438606, 2025).
cancer (continued). "This hypothesis aligns with findings from other cancer types, as well as preclinical models, where PROX1 facilitates lymphatic endothelial cell identity and remodeling." (PMID 40843762, 2025). "Also, it was discovered that PROX1 facilitated cancer spread via triggering WNT signaling to preserve β-catenin stability and encourage nuclear translocation of β-catenin." (PMID 40660330, 2025). "All these cases had carcinomas with positive PROX1 expression (100%)." (PMID 40660330, 2025). "PROX1 expression was mostly positive in high-grade carcinomas (28 instances, 84.8%)." (PMID 40660330, 2025). "This was following the IHC data, where α-SMA expression in cancerous tissue was markedly higher than that in paired normal tissue, with α-SMA-positive PROX1-expressing cancer cells exhibiting significantly higher invasive potential than those with null α-SMA expression." (PMID 38244581, 2024). "However, it is unclear how PROX1 and its downstream effectors affect cancer cell glucose metabolism and how this ultimately affects CRC carcinogenesis and progression." (PMID 36594098, 2023). "Finally, it should be noted that the opposing roles of ANRIL and GAS5 as tumor promoter versus tumor suppressor likely reflect the ambivalent role of PROX1 in cancer." (PMID 37407839, 2023). "In addition, PROX1 plays an important but ambivalent role in cancer as either oncogene or tumor suppressor, depending on the cancer type and context." (PMID 37407839, 2023). "Again, to provide preliminary indications of the clinical relevance of our identified mechanism of metabolic regulation in cancer involving PROX1, SIRT3, and EZH2, we examined the correlations between these protein expression levels in CRC patient tissues and clinical parameters and prognosis." (PMID 36594098, 2023). "Collectively, these discoveries suggest the role of PROX1 in metabolic reprogramming in cancer." (PMID 36594098, 2023). "Comparing HCC in the choline deficient model and choline supplemented model, significant methylation differences were seen in 11 genes previously associated with cancer (hypermethylation of TRAP1, SLC38A3, CHRM1, EDN2, and PROX1; hypomethylation of ALDH1B1, FTCD, FASTKD2, FAM96A, and ARHGAP15)." (PMID 36474183, 2022). "PROX1 (Prospero-related homeobox 1), as a type of transcription factor that plays a key role in the formation of lymphatic vessels in animal embryonic development, has been proven to promote or suppress cancer in a variety of malignant tumors." (PMID 35342346, 2022). "Additionally, patients with high PROX1 expression had a worse prognosis according to cancer stage (pStage: I–II vs. III–IV), N status (pN: N0 vs. N1-3), lymphatic vascular invasion (negative vs. positive), and vascular invasion (negative vs. positive)." (PMID 35885529, 2022). "Together, these results indicate that PROX1 plays an important role in the anti-proliferative effect of rapamycin and suggest that PROX1 protein level might be a useful marker for anti-cancer therapy of rapamycin in HCC." (PMID 35159256, 2022). "Prox1 expression levels are correlated with cancer progression and prognosis." (PMID 34183992, 2021). "Prox1 may be promoting proliferation in cancer through the inhibition of these retinoic acid signaling pathways." (PMID 33263009, 2020). "Interestingly, a major transcription factor of LECs, Prox1, was found to be overexpressed in multiple cancers, promoting not only lymphangiogenesis but also cancer cell migration capacity as well as invasiveness." (PMID 33263009, 2020). "Although cytoplasmic PROX1 may not exert its transcription factor activity, recent reports have shown that evaluation of cytoplasmic PROX1 in cancer patients may have a predictive value." (PMID 31060342, 2019).
cancer (continued). "The hypothesis related to the presence of PROX1 in the cytoplasm of cancer cells hint at a possibility of enrichment and activation of PROX1 in the cytoplasm before being translocated to the nucleus to become functionally active." (PMID 31060342, 2019). "Furthermore, we linked long-term proliferative capacity in a patient-derived model of CRC to a lowly abundant PROX1-positive cancer stem cell subtype." (PMID 31451731, 2019). "Finally, we observed that PROX1 is expressed in most of the examined FTC cases with high inter-individual variability, whereas all archived cancer tissues showed cytoplasmic and homogenously distributed PROX1 protein staining." (PMID 31060342, 2019). "It seems that this communication between FGF2 and PROX1 may be a very important mechanism regulating the spreading of cancer cells, which can metastasize via the lymphatic or vascular route depending on the analyzed case." (PMID 31717665, 2019). "In certain cancers PROX1 appears to transcriptionally suppress MMP14 expression." (PMID 31560170, 2019). "Dysregulation of PROX1 expression has been detected in a variety of human cancers, which suggests that it may be involved in tumorigenesis." (PMID 29371975, 2017). "This suggests that Prox1 may function either as a suppressor gene, or as an oncogene, depending on the tissue and cancer type context." (PMID 29371975, 2017). "Further, overexpression of PROX1 potentiates intestinal adenoma development, suggesting its important role in formation and growth of in situ lesions, which may progress to carcinoma." (PMID 28854215, 2017). "The difference in miR-9 expression by cancer type could be due to promoter activity of miR-9, whether through PROX1, Snail1, or hypermethylation." (PMID 27447934, 2016). "Moreover, we recently showed that Prox1 acts as tumor suppressor gene in nervous system related cancers by regulating basic components of the cell cycle machinery, including Cyclins, p27-Kip1 and Cdc25A, to induce cell cycle arrest." (PMID 25674048, 2014). "Prox1 produced by cancer cells may also trigger lymphangiogenesis from lymphatic and blood endothelial cells in OSCCs." (PMID 24647631, 2014). "PROX1 is multifunctional protein whose physiological functions may change according to developmental stage, organ, or type of cancer." (PMID 24797520, 2014). "We speculate that, by eliminating PROX1-mediated regulation of cell differentiation, down-regulation of PROX1 may be an important phenomenon in the progression from normal to precancerous cells or in situ establishment of early cancer status." (PMID 24797520, 2014). "Nevertheless, the exact mechanisms by which PROX1 regulates the differentiation and proliferation of cancer cells to influence overall prognosis are largely unknown." (PMID 24797520, 2014). "Regulation of cell cycle exit by Prox1 was previously shown in several developing tissues and in cancer and evidence that Prox1 may regulate p27Kip1 transcription by directly binding to its promoter was also observed." (PMID 24503550, 2014). "Diverse results propose different roles for PROX1 in different cancer types." (PMID 21970873, 2011). "It has been suggested that PROX1 has a similar role in human cancer." (PMID 21970873, 2011). "Prox1 facilitating cell proliferation makes great contributions to cancer progression." (PMID 23675176, 2010). "We suggest that Prox1 may exert its known influence on embryonic development, organ morphogenesis, and cancer through its ability to counteract Notch1 signaling." (PMID 21203589, 2010). "Additionally, the anti‐tumourigenic effect of ERβ in cancer cells could be a combination of downregulation of oncogenes such as PROX1, Myc, and MYB along with increased DNA repair capacity and induction of apoptosis." (PMID 36207986, 2023).
cancer (continued). "In summary, our present study reveals a novel function of PROX1 in cancer cell metabolism, i.e., PROX1 recruits EZH2 to the SIRT3 promoter and represses SIRT3 transcription, which may represent the molecular mechanism underlying the observed biological consequences." (PMID 36594098, 2023). "Together, these results suggest that PROX1 plays a critical role in the anti-proliferative effect of rapamycin on HCC and that the upregulation of PROX1 by an MTOR inhibitor might be a useful molecular marker for predicting the efficacy of its anti-cancer effect on HCC cells." (PMID 35159256, 2022). "The genes involved in angiogenesis were selected by RNA-seq, and the impact of PROX1 on vascularization potential was investigated using human umbilical vein endothelial cells (HUVECs) cultured in conditioned medium collected from FTC- or SCT-derived cancer cell lines after PROX1 silencing." (PMID 31717665, 2019). "Interestingly, the study also suggested that there located a transcription factor Prospero-related homeobox 1 (PROX1) downstream of Yiya, which might be involved in cancer metastases." (PMID 27391432, 2016). "The integrative analysis identified PROX1+ LEC subsets, JAM2+ BECs, COL1A1+ stromal cells, PTPRC+ leukocytes, including MZB1+ plasmablasts, KRT19+ cancer cells, and MKI67+-proliferating cells." (PMID 41249124, 2025). "Unbiased clustering using UMAP identified several cell types, including KRT19+ cancer cells, CD3E+ T cells, MS4A1+ B cells, MZB1+ plasmablasts, FLT3+ dendritic cells (DCs), and PROX1+ LECs, which were then visualized within the tissue context." (PMID 41249124, 2025). "It has also been observed that in CRC, the dysregulated Wnt pathways influence the transcription factor Prospero homeobox 1 (PROX1)., which is overexpressed in multiple cancers." (PMID 38244581, 2024). "In cancer cells, the Ser79 phosphorylation of Prox1 by AMP-activated protein kinase promotes Prox1 degradation through the recruitment of the CUL4-DDB1 E3 ubiquitin ligase complex." (PMID 37091974, 2023). "Accordingly, in endothelial cells, Prox1 negatively regulates the metalloprotease MMP14, which is involved in cancer invasion and angiogenesis." (PMID 37508533, 2023). "c-Myc is the upstream positive regulator of the Prox1-inhibited genes (GLUT1, HK2, and PDK1), identified here, as well as the Warburg effect in cancer cells." (PMID 37508533, 2023). "For example, MAPK8IP2, ADAMTS12, and CHAF1B were upregulated in over five cancer types, while HHIP, PROX1, and PLCG2 were downregulated in over five cancer types." (PMID 35654793, 2022). "It was recently reported that Prospero-related homeobox 1 (PROX1), an important transcription factor responsible for the development of several tissues such as lymphatics or liver, contributes to cancer development and progression." (PMID 35159256, 2022). "PROX1 was highly expressed in SCLC cell lines, while its knock-down (via a constructed shRNA-lentivirus) significantly reduced the cancer cell proliferation rate." (PMID 35885529, 2022). "Differential hydroxymethylation is found in thousands of genes, most significantly in genes related to pancreas development or function (GATA4, GATA6, PROX1, ONECUT1, MEIS2), and cancer pathogenesis (YAP1, TEAD1, PROX1, IGF1)." (PMID 33077732, 2020). "The homeobox gene PROX1 plays a key role in the embryonic development of different organs such as the lens, liver, pancreas, central nervous system and lymphatic system and may function as a suppressor gene or an oncogene, depending on the tissue and cancer type." (PMID 31060342, 2019). "Here, we show that PROX1 suppresses the transcription of MMP14, a metalloprotease involved in angiogenesis and cancer invasion, by binding and suppressing the activity of MMP14 promoter." (PMID 29934628, 2018). "Our work reveals that PROX1 regulates MMP14 expression in several cellular contexts, and thus represents an important modulator of normal and cancer cell behaviour." (PMID 29934628, 2018).
cancer (continued). "Taken together, demonstration that PROX1 negatively regulates MMP14 in normal tissues and in cancer supports the general nature of this signalling axis and its potential importance in physiological and pathological processes." (PMID 29934628, 2018). "The expression of Prox1 and 5'-nucleotidase by MDA-MB-231 cells is interesting, possibly explained by the poor differentiation of these cancer cells." (PMID 18325094, 2008). "Hydroxymethylation in genes such as GATA4, GATA6, PROX1, ONECUT1, and MEIS2, which plays an important role in development and functioning of pancreas, as well as in genes YAP1, TEAD1, PROX1, IGF1, were found involved in cancer pathogenesis." (PMID 40230862, 2025). "Cancer cells lacking the LKB1-AMPK axis rely on PROX1 to maintain intracellular BCAA levels, leading to enhanced mTOR signaling, tumorigenesis, and invasiveness." (PMID 40438606, 2025). "PROX1 was (predominantly) expressed negatively in carcinomas with no lymph-vascular invasion (P = 0.000)." (PMID 40660330, 2025). "The greater percentage of stage I and stage II cases had carcinomas revealed negative PROX1 expression (10 cases, 76.9%, P = 0.000)." (PMID 40660330, 2025). "Most low-grade carcinomas had negative PROX1 expression, including all five cases of ACC (100%), and six cases of low-grade MEC (85.7%)." (PMID 40660330, 2025). "Importantly, PROX1 was localized, similar to α-SMA, mainly in the cytosolic and membranous portions of the cancer cells." (PMID 38244581, 2024). "Given the high recurrence rate of CRC post-surgery and the existing knowledge gaps about recurrence mechanisms, our study aimed to elucidate the relationship between elevated PROX1 and α-SMA expression, cancer progression, clinical outcomes, and their influence on CAFs in the CRC TME." (PMID 38244581, 2024). "We have shown that CCAR2 facilitates long-range chromatin interactions between distal enhancers and promoters of tumor-promoting genes such as PROX1, MACC1, and CDH2 in cancer cells, suggesting that CCAR2 activates oncogenic gene transcription by regulating chromatin architecture." (PMID 37524873, 2023). "Several studies used PROX1 in order to quantify intra-and peritumoral lymphangiogenesis, mainly expressed as LVD, and further correlated this to clinicopathological variables and cancer prognosis." (PMID 35885529, 2022). "We also observed that PROX1 might be in close relation with the pro-angiogenic factor FGF2, which suggests that PROX1 is engaged in the axis of cancer angiogenesis mechanism." (PMID 31717665, 2019). "Therefore, we tested if the PROX1-induced decrease in MMP14 affects the ability of endothelial and cancer cells to invade into 3D crosslinked fibrin." (PMID 29934628, 2018). "Five-year cancer-specific survival (CSS) was not significantly different for PDAC patients with low PROX1 expression compared to those with high expression (log-rank, p = 0.174)." (PMID 27411302, 2016). "786-O cells were nearly negative for PROX1 expression; however, the three other cancer cell lines as well as HKC cell clearly expressed PROX1." (PMID 24797520, 2014). "Furthermore, the role of Prox1 and FOXC2 in cancer cell growth and invasion was evaluated in cultured OSCC cells." (PMID 24647631, 2014). "Collectively, these previous discoveries suggested the role of PROX1 in metabolic reprogramming in cancer, but this hypothesis has not been conclusively demonstrated, and sufficient data are lacking on the specific role of PROX1 in CRC cell glucose metabolism." (PMID 36594098, 2023). "Thus, it was rational to hypothesize that PROX1 interacts with transcriptional coregulators or epigenetic modifiers to regulate SIRT3 expression and thus modify cancer cell behavior." (PMID 36594098, 2023).